STAT3 (signal transducer and activator of transcription 3)
Diseases named in the same sentence as STAT3 in open-access papers (continued):
Sharing a sentence is not in itself a finding about the gene and the disease.
cancer (continued). "CuE can also suppress angiogenesis by inhibiting the VEGFR2-mediated JAK2 − STAT3 signalling pathway and cancer cell metastasis by inhibiting depolymerization of actin filaments." (PMID 35193614, 2022). "The continuous activation of STAT3 was shown to be a strong promoter of tumorigenesis by stimulating proliferation, survival and metastasis of cancer cells." (PMID 35372504, 2022). "ALA binds to AKR1C1 and shows strong suppression effect against AKR1C1, resulting in an inhibition of STAT3, to inhibit cancer proliferation and metastasis." (PMID 35370661, 2022). "The over-activated STAT3 signaling in cancer cells induces target gene expression; these genes include cyclinD1 (promotes cell growth) and the BCL2 family member MCL-1 (reduces apoptosis)." (PMID 35810312, 2022). "Numerous RBPs (e.g. Lin28, IGF2BPs and Musashi-1/2) and DBPs (e.g. NF-κB, c-myc and STAT3) are overexpressed and/or overactivated in human cancers, promoting tumorigenesis and cancer development." (PMID 35410300, 2022). "The ability of SBT-100 to penetrate the cell membrane and bind intracellular KRAS and STAT3 translates into functional suppression of cancer growth and proliferation in vitro and in vivo." (PMID 35886918, 2022). "Meanwhile, there were pieces of evidences that the inflammation induced by IL-6 and IL-1β was through the MAPKs, NF-ΚB, and STAT3 pathways in many cancers." (PMID 35280511, 2022). "STAT3 is persistently activated in cancer cells and functions as a positive transcription factor to induce the expression of various pro-survival genes that play roles in oncogenic processes." (PMID 35269802, 2022). "A systems biology approach suggested that Pdia4 activates Stat3 and its downstream pathway in cancer stroma." (PMID 35170261, 2022). "The molecular targets for chemopreventive agents described in this review (Nrf2, STAT3, and Src) have shown to be promising candidates with chemopreventive potential in various cancer cell lines or carcinogen-induced tumorigenesis models in animals." (PMID 36145523, 2022). "One of the main pathways involved in EC is the interleukin-6/STAT3 signaling pathway, which is upregulated in several other cancers." (PMID 35511379, 2022). "MMPs are among its target genes, which in this way STAT3 is involved in regulating cancer cell migration." (PMID 35281008, 2022). "Signal transducer and activator of transcription 3 (STAT3) is a key transcriptional regulator of many protumorigenic processes and is persistently activated in many types of human cancer." (PMID 34953855, 2022). "Meanwhile, the increased phosphorylation of STAT3 was implicated in cell proliferation that is consistent with the function of STAT3 in cancers." (PMID 36293016, 2022). "STAT3 activation has been shown to inhibit the antitumor functions of CD8+ T cells in various cancers." (PMID 35530361, 2022). "JAK2/STAT3 has also been confirmed to be critically involved in the growth and metastasis of multiple cancers, including OCSS." (PMID 35513871, 2022). "STAT3 is typically activated in cancer cells via various upstream factors such as cytokines and growth factors." (PMID 35228642, 2022). "Further, JAK 1 expression and STAT3 expression were downregulated by fisetin treatment in cancer cells." (PMID 36558146, 2022). "The constitutive activation of STAT-3 has been described in various cancer cells, including downregulation of apoptotic gene transcription and upregulation of proto-oncogene expression." (PMID 36389843, 2022). "Aberrant activation of STAT3 has been observed in many cancers, which serves as a bona fide target in cancer therapies." (PMID 35628304, 2022). "STAT3 is known to regulate multiple hallmarks of cancer such as proliferation, cell survival, angiogenesis and immune evasion." (PMID 35053502, 2022). "A lot of literature evidence describes the critical role of constitutive STAT3 signaling activation in cancer genesis and progression." (PMID 35956786, 2022).
cancer (continued). "STAT3 is not only activated in cancer cells, but also becomes hyperactivated in immune cells within the OSCC TME." (PMID 36231093, 2022). "The STAT3/CEBPb-miR-21a/b/181b-MII1 axis provided an effective immunotherapeutic manner against cancer." (PMID 35634311, 2022). "This view was documented by silencing STAT3 gene which induced a strong suppression of total p‐STAT3 and Bcl‐2 protein levels, and a dramatic reduction of transcriptional levels of cancer‐related cytokines, genes and cell survival." (PMID 34850540, 2022). "TAMs-derived CCL5 activates STAT3 signaling in cancer cells and increases cell migration, EMT and cell invasion as well as supports cancer stem cell self-renewal." (PMID 36338516, 2022). "STAT3 is a key transcription factor belonging to the STAT family that promotes cancer cell proliferation, and invasion, and also induces angiogenesis and immunosuppression." (PMID 36620587, 2022). "We chose STAT3 as a target, given that this oncogenic TF has been targeted with the previous generation of decoy ODNs and is a well known but undruggable target in cancer therapy." (PMID 35847174, 2022). "Ptprt controls JAK/STAT signaling by dephosphorylation of STAT3, which is frequently dysregulated in human cancer, including AML." (PMID 34741119, 2022). "The IL-6/STAT3 signaling pathway consistently demonstrates aberrant hyper-activation in cancer patients." (PMID 34976184, 2022). "IL-6/JAK/STAT3 pathway is predicted to be activated in TAb2 tumors, which is often hyperactivated in various types of cancer that correlates with poor prognosis." (PMID 35366939, 2022). "Stat1 expression and activation were reduced in cancer cell and stromal cell compartments of Tyk2Δ/Δ tumors, respectively, whereas Stat3 expression and activation remained unchanged." (PMID 36185806, 2022). "A previous study suggested that combining anti-EGFR and anti-STAT3 agents would prove a practically effective mode of cancer suppression." (PMID 36145523, 2022). "In particular, the phosphorylation of tyrosine 705 of STAT3 induces expression of several target genes that exacerbate cancer progression." (PMID 35927628, 2022). "Aberrant STAT3 activity promotes malignancy, and acts as a metabolic switcher in cancer cell metabolism, contributing to resistance to TKI nilotinib." (PMID 36033954, 2022). "It is previously reported to promote gastric carcinogenesis and inflammation-cancer progression through the activation of STAT3 in our recent study." (PMID 36266267, 2022). "Among all these proteins, STAT3 seems to be a key protein for the creation of cancer microenvironment and be involved in MDSC development modulated by miRNAs." (PMID 35634311, 2022). "Inhibition of STAT3 activation is known as one of the critical resveratrol-induced events in cancers, and the statuses of STAT3 expression and signaling determine the fate of resveratrol-treated ATC cells." (PMID 36430869, 2022). "In NPC, IL‐6 activates signal transducer and activator of transcription 3 (STAT3) and promotes the proliferation, migration, and invasion of cancer cells." (PMID 36039641, 2022). "The Signal Transducer and Activator of Transcription 3 (STAT3) is a transcription factor that is upregulated in many cancers." (PMID 35207558, 2022). "ERK1/2 and Janus-activated kinase 1 (JAK1) affect cancer cell proliferation, metabolic regulation, and cancer cell metastasis through the regulation of STAT3 amino acid phosphorylation levels in invasive ovarian cancer cells." (PMID 36523985, 2022). "For instance, STAT3 transcriptionally regulates CCR7 to promotes cancer, while miR-4500 inhibits STAT3 expression by targeting the STAT3 3′-3UTR region and thus suppressed cancer development." (PMID 36227136, 2022). "There are few treatment options currently available for TNBC; thus, given its importance to cancer, STAT3 is a potential cancer therapeutic target and is the focus of drug discovery efforts." (PMID 36009550, 2022).
cancer (continued). "By reviewing studies on STAT3 in cancer settings, we attempt to relate the STAT3 role in memory formation to antitumor immunity." (PMID 35270020, 2022). "Particularly, STAT3 is of interest in cancer biology that can mediate and even promote cancer progression." (PMID 35593388, 2022). "Aberrant STAT3 hyperactivation is present in most human cancers and is integral to provoking malignant phenotypes." (PMID 36613579, 2022). "Taken together, this evidence indicated that BBR exerts anti-inflammatory and cancer preventive activity possibly through the modulation of JNK/STAT3 and β-catenin signaling." (PMID 35215376, 2022). "IL‐6‐dependent STAT3 activation induces M2 polarization while inhibiting M1 activation, and this promotes cancer progression and reduces patient survival." (PMID 35356799, 2022). "It is well documented that STAT3 signaling regulates cancer progression and survival, and it is also involved in the Warburg effect." (PMID 35742904, 2022). "Based on the STAT3-mediated soluble factor production from cancer and stromal cells 18, 41, the conditioned media (CM) from H1299 and A549 cells that survived 5 days of 17-AAG treatment were added to naïve NSCLC cells." (PMID 34987637, 2022). "Post-transcriptional inhibition of STAT3 synthesis in cancer cells using small interfering RNA (siRNA) is the most common method of inhibiting the STAT3 pathway." (PMID 36291659, 2022). "Activation of STAT3 stimulates the expression of several genes that play a significant role in cancer development, emphasizing the importance of STAT3 in HCC." (PMID 35883021, 2022). "On the other hand, few effective therapies that target STAT3 signaling for the treatment of cancer in clinical practice have been developed." (PMID 36010693, 2022). "STAT3, as a multifunctional regulator in cancer formation, development, and metastasis, can influence all cancer hallmarks through the following five ways." (PMID 35356799, 2022). "Several lines of evidence suggest that STAT3 plays a functional, pivotal role in modulating the biology of cancer cells, by affecting their energy metabolism and the metabolism of glucose and lipids." (PMID 35053416, 2022). "Persistent STAT3 activation in malignant cancer cells mediates extremely widespread functions, including cell growth, survival, angiogenesis, and invasion and contributes to an increase in inflammation-associated tumorigenesis." (PMID 36010693, 2022). "Previously, brevilin A has been identified as a janus kinases (JAKs) inhibitor, and exhibits a potent repression on signal transducer and activator of transcription 3 (STAT3) signaling and cancer cell growth." (PMID 35774606, 2022). "As a crucial signaling pathway, JAK2/STAT3 plays a critical role in various stages of cancer development." (PMID 36014474, 2022). "Chronic inflammation promotes cancer progression by increasing the production of pro-tumorigenic cytokines, mainly IL-6, IL-17A, IL-22 and IL-23, which activate NF-κB and STAT3 signaling pathways." (PMID 35387985, 2022). "The therapeutic implications of this observation have attracted attention as a target for cancer therapy, and several Stat3 inhibitors have been designed." (PMID 36010614, 2022). "Signal Transducer and Activator of Transcription 3 (STAT3) plays a crucial role in cancer development and thus is a viable target for cancer treatment." (PMID 36542668, 2022). "Constitutively active IL-6/JAK/STAT3 signaling drives cancer cell proliferation and invasiveness while suppressing apoptosis, and STAT3 enhances IL-6 signaling to promote a vicious inflammatory loop." (PMID 35371975, 2022).
cancer (continued). "This raises the possibility that BPA’s mechanism of action in certain cancers is dependent on STAT3/miR-21 signaling and regulation, which together contribute to poor prognosis and outcomes." (PMID 35955412, 2022). "It highlights the possibility of using IL-6/STAT3/SMG1 pharmacological inhibitors to sensitize them for cancer immunotherapy." (PMID 36443756, 2022). "Therapeutically exploiting STAT3 activity in cancer appears to be more promising therapeutic approach." (PMID 36221123, 2022). "After IL-6 treatment, STAT3-mediated change of chromatin structure was significantly increased, which played a role in inflammation-mediated cancers." (PMID 36231093, 2022). "Both inhibitors significantly reduced the activation of STAT3 after a short treatment of BM macrophages, followed by 2 h of incubation with apoptotic cancer cells." (PMID 36496973, 2022). "Combination therapy enhances DNA damage and apoptosis in cancer cells, as STAT3 activation is important for cell survival." (PMID 36145523, 2022). "Overexpression of a constitutively activated STAT3 mutant rescues Niraparib-induced cancer cell apoptosis." (PMID 36324587, 2022). "Due to its function in various biological processes and disorders, including cancer, the transcription factor STAT3 has been extensively studied for over two decades." (PMID 36313702, 2022). "STAT3 maintains a pro-carcinogenic inflammatory microenvironment during malignant transformation and cancer progression, and mediates the production of immunosuppressive cytokines in the TME, which is also a biomarker indicative of poor survival in TNBC." (PMID 34875483, 2022). "Numerous studies have proven that signal transducer and activator of transcription 3 (STAT3) affect EMT in cancer." (PMID 35677538, 2022). "Taking into account the widely recognized role of AKT and STAT3 signaling in cancer cell proliferation, a possible modulation of this signaling in HT-29 cells by pterostilbene was also evaluated." (PMID 35056682, 2022). "Decreased STAT3 expression retards the generation of pro-inflammatory cytokines needed to drive cancer growth, invasion, and metastasis, while increased levels of activated caspase-3 will commit the A549 cells to apoptosis." (PMID 35523904, 2022). "TAMs are required for CSCs self-renewal and maintenance in different cancer types via activation of the STAT3/NF-κB pathway." (PMID 36207500, 2022). "In this review, STAT3, its regulation, its roles in cancer stemness maintenance, and its relationship with p63 are elucidated." (PMID 36061200, 2022). "STAT3 suppresses anti-tumor immune responses and promotes the proliferation and migration of cancer cells." (PMID 36545470, 2022). "Previous studies have shown that suppression of STAT3 using specific inhibitors suppresses the growth of cancer cells." (PMID 36428714, 2022). "Heteronemin inhibits ERK1/2, PI3K, STAT3, and NF-κB activation in several types of human cancer cells." (PMID 35705962, 2022). "Aberrant STAT3 activation has been identified as a key driver of tumorigenesis in many types of cancers, including MM." (PMID 35326392, 2022). "The effectiveness of the JAK inhibitors in the RM9 cancer cachexia model was most likely due to the elevation of IL-6 family of cytokines as well as other STAT3-activating cytokines." (PMID 35785158, 2022). "Despite this frustration, STAT3 still remains a valuable target for the discovery of anti-cancer drugs." (PMID 35158821, 2022). "At the molecular level, NF-kB was found to be inhibited by DMF and, in the latter two cancer types, the de-phosphorylation of STAT3 was also induced." (PMID 35743211, 2022). "Meanwhile, we found that cancer-associated signaling pathways, such as hypoxia pathway, MAPK, Wnt and STAT3 signaling pathways, were also downregulated following NAC." (PMID 35361730, 2022). "When EGFR activity in cancer cells is inhibited, phosphorylation of STAT3 is diminished, thereby inhibiting cancer cell proliferation and improving resistance to the drug." (PMID 36291659, 2022).
cancer (continued). "In as much as IL-6 and STAT3 activation can enhance the proliferation of cancer cells in various solid tumors as well as hematopoietic malignancies, considerable effort is now focused on the development of STAT3 inhibitors as anti-cancer agents." (PMID 35406728, 2022). "STAT-3 is one of the members of STAT family which is known to be activated in different types of cancer." (PMID 35300689, 2022). "Potential targets of statins for cancer treatment identified by LIGHTHOUSE included STAT3, CCND1, AKT1, and CCL2." (PMID 36246574, 2022). "The study concluded that silibinin had chemoprotective potential via the IL-6/STAT3 pathway, giving it dual beneficial activity in cancer and inflammation, both of which are present in colitis-associated cancer." (PMID 36145523, 2022). "We introduce the STAT3 pathway inhibitors and the novel drug delivery systems in preclinical studies and clinical trials for cancer treatment." (PMID 35356799, 2022). "Our data show that minocycline directly binds and inhibits LYN activity, leading to inhibition of EMT and metastasis of cancer cells by suppressing STAT3 signaling." (PMID 35414768, 2022). "STAT3 is widely activated in multiple human cancers and has been an attractive target for cancer therapeutic." (PMID 36207761, 2022). "LIF can function as upstream mediator of JAK1/STAT3 signaling in preventing differentiation of cancer cells." (PMID 35773731, 2022). "Since STAT3 is also known to induce the expression of PD-L1, it is expected to exert dual effects by inhibiting STAT3 to prevent cancer progression and targeting PD-L1 to prevent immune exhaustion." (PMID 35927628, 2022). "Stat3 is a transcription factor with many biological functions, and the hyper-activation of Stat3 widely regulates the malignant progression of cancer cells." (PMID 34991668, 2022). "STAT3 has been shown to play a pro-cancer role in a variety of cancers and inhibitors of STAT3 are used in pre-clinical and clinical studies." (PMID 36291659, 2022). "In an independent study, inhibition of CuI on p-STAT3 was confirmed across an array of cancer cells." (PMID 36355554, 2022). "The authors also found that STAT3 activation enhances the spread of cancer to lungs and bones in mice." (PMID 35682652, 2022). "MDSCs in TME released IL-6 to constantly activate STAT3 in cancer cells, which conferred invasive potential to cancer cells, induced epithelial mesenchymal transition (EMT) of cancer cells, and enhanced cancer cell stemness." (PMID 35267547, 2022). "Although Stat3 is a validated target for the discovery of novel anti-cancer drugs, the discovery and development of potent small molecule inhibitors has proved to be a significant challenge." (PMID 35276290, 2022). "Studies conducted on Withaferin A have noted the compound’s ability to target multiple oncogenic signaling pathways such as NF-κB, Akt, NOTCH, STAT3, and estrogen receptor α (ER-α); these pathways are often found active in human cancers." (PMID 36339589, 2022). "Targeting STAT3 is a prevalent strategy for the treatment of various cancers, inflammatory and autoimmune disorders." (PMID 36536188, 2022). "This demonstrates a new proof in inflammation-cancer transition of CRC involving CypB-supported STAT3 activation and their interaction with downstream ncRNAs induced by IL-6 cascades." (PMID 36266267, 2022). "Signal transducer and activator of transcription 3 (STAT3) phosphorylation in the cancer cells cultured on polymer X was upregulated by the fibronectin-integrin α5-Janus kinase 2 (JAK2) axis and maintained by the cytosolic LMO2/LBD1 complex." (PMID 36359204, 2022). "Naphthoquinones are potent anti-invasive agents acting on EMT (endothelial mesothelial transition) of cancer stem cells and STAT3 signaling cascades." (PMID 36500400, 2022).